MLH3 (mutL homolog 3)
Diseases named in the same sentence as MLH3 in open-access papers (continued):
Sharing a sentence is not in itself a finding about the gene and the disease.
glioma (4 papers, 2016 to 2025). A benign or malignant brain and spinal cord tumor that arises from glial cells (astrocytes, oligodendrocytes, ependymal cells). "The methylation of the MLH3 promoter is a new finding, and is reported to appear in 27 % of astrocytomas, although its role in glioma is yet to be investigated." (PMID 26865861, 2016). "Another study performed in low-grade gliomas reported a consistent signature in the methylation of MGMT, MLH3, RAD21, and SMC4 promoter region predictive value for response to temozolomide." (PMID 35359376, 2022).
ovarian carcinoma (4 papers, 2015 to 2023). A malignant neoplasm originating from the surface ovarian epithelium. "In our study, only one likely pathogenic frameshift variant c.1544del in the MLH3 gene was detected in a patient with ovarian cancer." (PMID 38201513, 2023). "The relationship between germline mutations in MLH3 and ovarian cancer risks remains unclear." (PMID 38201513, 2023).
cervical carcinoma (3 papers, 2014 to 2021). A carcinoma arising from either the exocervical squamous epithelium or the endocervical glandular epithelium. "For cervical carcinoma, MLH3 had some diagnostic ability, but its sensitivity was poor (35.9 %) despite high specificity (96.15 %)." (PMID 33602229, 2021). "Thus, it is more accurate to examine the association between the linkage disequilibrium of two MLH3 SNPs and the risk of cervical carcinoma, because the function of a certain protein is determined by two or more amino acid sites." (PMID 24759751, 2014).
male infertility (3 papers, 2017 to 2023). The inability of the male to effect fertilization of an ovum after a specified period of unprotected intercourse. "The loss of function of the DNA mismatch repair gene MLH3 can lead to male infertility with azoospermia or severe oligozoospermia." (PMID 36766254, 2023). "Human MLH3 (hMLH3) gene has been suggested to play a role in the DNA mismatch repair mechanism, while it may also be associated with abnormal spermatogenesis and subsequently male infertility." (PMID 28157160, 2017). "SNPs in MLH1 and MLH3 have been statistically associated with male infertility in some studies focusing on candidate genes (i.e., not GWAS), but there have not been validation studies." (PMID 34408140, 2021). "Human MLH3 gene may be also associated with spermatogenesis and male infertility, as a negative impact of the Pro844 to Leu of the MLH3 gene (rs175080 polymorphism) on sperm parameters has been recently found." (PMID 28157160, 2017).
astrocytoma (2 papers, 2002 to 2016). "Whether genetic alteration of MLH3 plays a role in astrocytoma formation remains to be determined." (PMID 12107846, 2002).
Azoospermia (2 papers, 2010 to 2023). Absence of any measurable level of sperm,whereby spermatozoa cannot be observed even after centrifugation of the semen pellet. "The only gene mapped to mouse chromosome 12 and human chromosome 14 with polymorphisms associated with azoospermia is MLH3, which causes a meiotic arrest." (PMID 21206922, 2010).
mismatch repair deficiency (2 papers, 2016 to 2025).
(CMMRD) syndrome (1 paper, 2025).
autoimmune disease (1 paper, 2018). A disorder resulting from loss of function or tissue destruction of an organ or multiple organs, arising from humoral or cellular immune responses of the individual to their own tissue constituents. "MLH3 and BIN1 gene have shown to be associated with Lupus, another severe autoimmune disease." (PMID 30666269, 2018).
cervical squamous cell carcinoma (1 paper, 2014). A squamous cell carcinoma arising from the cervical epithelium. "Association between MLH3 polymorphisms and the risk of cervical squamous cell carcinoma and CIN III in all and HPV-positive subjects." (PMID 24759751, 2014). "Association between the MLH3 Pro844Leu, Thr942Ile genotype and the risk for CIN III and cervical squamous cell carcinoma stratified by various environmental factors." (PMID 24759751, 2014). "MLH3 genotypes and the risk of all CIN III and cervical squamous cell carcinoma." (PMID 24759751, 2014).
colorectal tumours (1 paper, 2002). "MLH3 is a mismatch-repair gene and mutation of this gene is associated with microsatellite instability in colorectal tumours." (PMID 12107846, 2002).
gastric cancer (1 paper, 2014). A primary or metastatic malignant neoplasm involving the stomach. "Furthermore, in a study of familial gastric cancer, no strong association was verified between 5 variants of MLH3 and gastric cancer risk." (PMID 24759751, 2014).
intestinal tumors (1 paper, 2017). "A chromosome 7 CNA deletion hotspot shared by Mlh3, Pms2 and Mlh1 mutant MEFs was also seen that had been previously identified in Mlh3−/−;Pms2−/− deficient intestinal tumors." (PMID 29069730, 2017). "Next, to assess SSA, we used gamma-irradiation to promote endogenous DSBs and show that Mlh1, Pms2 and Mlh3 mutations suppress CNAs, including recurrent CNA hotspots that we previously identified in mouse dMMR intestinal tumors." (PMID 29069730, 2017). "Furthermore, an Mlh1 (but not other MutL homologue) mutation dependent chromosome 12 CNA amplification hotspot, which had also been previously identified in Mlh3−/−;Pms2−/− intestinal tumors, was observed." (PMID 29069730, 2017). "Previously, we identified dMMR enriched recurrent CNAs in mouse Mlh3−/−;Pms2−/− intestinal tumors on chromosomes 7 and 12, which were not present in paired normal mucosa." (PMID 29069730, 2017).
lung adenocarcinoma (1 paper, 2020). A carcinoma that arises from the lung and is characterized by the presence of malignant glandular epithelial cells.
lupus (1 paper, 2018). "MLH3 gene is known for its function in repair mismatched DNA and risk for thyroid cancer and lupus." (PMID 30666269, 2018).
meningioma (1 paper, 2022). A generally slow growing tumor attached to the dura mater. "Finally, MLH3 losses on 14q completes the set of altered genes that are located in cytogenetic hotspots of meningioma." (PMID 36011000, 2022).
myotonic dystrophy type 1 (1 paper, 2013). Steinert disease, also known as myotonic dystrophy type 1, is a muscle disease characterized by myotonia and by multiorgan damage that combines various degrees of muscle weakness, arrhythmia and/or cardiac conduction disorders, cataract, endocrine damage, sleep disorders and baldness. "A role for MLH3 had also been suggested from findings in a mouse model of myotonic dystrophy type 1 in which knockout of Pms2, encoding MLH1's major binding partner, reduced the rate of somatic CTG expansion by ∼50%, but did not eliminate somatic expansions." (PMID 24204323, 2013).
papillary thyroid cancer (1 paper, 2018). "In papillary thyroid cancer, oxidative stress causes heavy DNA damage and the downregulation of MMR-associated genes (including MLH3 and PMS1)." (PMID 30451877, 2018).
cancer (34 papers, 2005 to 2025). A tumor composed of atypical neoplastic, often pleomorphic cells that invade other tissues. "This is the first study reporting on MLH3 rs28756991 polymorphism (Arg797His) and its relation to cancer risk; however, other functional polymorphisms in the MLH3 gene have previously been shown to confer cancer susceptibility." (PMID 22623965, 2012). "There was also evidence implying a reduced cancer risk, with marginal significance, for MLH3 rs2875991 ‘A’ allele under recessive genetic model (adjusted OR: 0.14; P = 0.078)." (PMID 22623965, 2012). "Germline mutations in MLH3 may increase cancer susceptibility through synergistic interactions with other MMR genes, whereas somatic mutations in MLH3 may trigger MSI independently, thereby facilitating the initiation and progression of Lynch-like EC." (PMID 41154599, 2025). "With regard to potential mechanisms of CAG expansion it is of interest that MSH3 and MLH3 appear to play relatively minor roles in classical MMR inasmuch as Msh3 and Mlh3 deficiencies result in weak mutator phenotypes and relatively low cancer predisposition phenotypes." (PMID 24204323, 2013). "Besides the well-known mismatch repair proteins, the MLH3 gene may also contribute to cancer susceptibility." (PMID 40356752, 2025). "In addition, while mutations in MSH3 and MLH3 have been implicated in a variety of cancers and cancer predisposition syndromes, PMS1 mutations have not been definitively associated with any cancer predisposition to date either in mice or humans (see omim.org/entry/600258?search=pms1&highlight=pms1)." (PMID 32589669, 2020). "These suggest the MLH3 mutation might be involved in the development of cancer." (PMID 24759751, 2014). "Unlike the robust nuclear distribution seen for the other targets, MLH3 shows a distinct nucleocytoplasmic distribution, as previously reported in somatic and cancer cell lines." (PMID 38749429, 2024). "Among the DNA-repair genes that did exhibit positive correlations in the cross-validation, MLH3 was almost uniformly hypomethylated in all three cancer types." (PMID 27683114, 2016). "The powers to detect the observed effect sizes in tobacco-smoking cases of Mixed Ancestry group remained sufficient for MSH3 rs26279 (97.53%) and MLH3 rs28756991 (85.05%), whereas borderline association of PMS1 rs5742938 with cancer was underpowered at 64.06%." (PMID 22623965, 2012). "Similarly to cancer tissues, in adjacent mucosal tissues, MLH3 correlated with PMS1 and PMS2 (R = 0.887 and R = 0.931, P < 0.000, respectively), but, additionally, MLH3 also correlated with MSH6 (R = 0.857, P < 0.0001)." (PMID 24484585, 2014).
cancer (continued). "Given all this, these four DDR genes (EME2, MSH4, MLH3, and SPO11) have been proved to take part in the pathogenesis, progression, and prognosis of cancers." (PMID 36816926, 2023). "A literature and COSMIC search revealed that several of these mutations have been detected in other model systems and other cancer subtypes, e.g. PARP-1 (V377S), ATR (K297 N), FANCA (G809 N), and MLH3 (I541V)." (PMID 30305041, 2018). "MLH3 is a DNA MMR gene, which plays vital role in cancer development." (PMID 29876008, 2018). "Frequent MLH3 methylation in IDHmt LGG has been reported previously; MLH3 may be involved in other cancer-relevant processes." (PMID 29368212, 2018). "For example, one isoform of MLH3 (uc010tuy.1), a DNA mismatch repair gene without significant changes at the overall mRNA level (log2FC=-0.04, FDR = 0.6), was significantly downregulated in the late stage of cancer (log2FC=-1.71, FDR = 0.006)." (PMID 24564989, 2013).
tumor (31 papers, 2002 to 2025). "Because the combination of Mlh3, Pms2 and Apc mutations accelerates tumor progression, we searched MPA GI tumor specific genetic changes associated with progression using high-resolution aCGH." (PMID 18551179, 2008). "To understand the role of Mlh3 in these processes, we used the wild type Apc allele as a tumor-associated in vivo reporter gene to analyze the mutation spectrum from MA GI tumors." (PMID 18551179, 2008). "Moreover, a mutated gene, MLH3, known being related to DNA mismatch repair, was found on the branch leading to the tumour subclone." (PMID 36451239, 2022). "Mlh3 nullizygosity significantly increased Apc frameshift mutations and tumor multiplicity." (PMID 18551179, 2008). "Furthermore, previous research indicated that 25% of MSI-H tumor samples exhibited MLH3 somatic mutations in 36 cases of CRC, suggesting that such mutations may also contribute to the development of MSI-H tumors." (PMID 41154599, 2025). "DelSIEVE identified many single point mutations on the branch leading to the two tumor subclones, including a reported CRC driver mutation in gene SYNE1, as well as a mutation related to DNA mismatch repair, in gene MLH3." (PMID 40855447, 2025). "MLH3 is a member of the DNA mismatch repair gene family, which is observed with a lower expression level in tumor samples compared with normal tissue." (PMID 36816926, 2023). "Two variants were found exclusively in cell 2 and not in its tumor (MMP1 and STAT3), whereas two variants were found only in the tumor from which cell 6 was derived (ERBB2 and MLH3)." (PMID 33917394, 2021). "We then examined the effects of Liuweidihuang wan in MLH3 (−/−) mice and MLH3 (−/+) mice with tumor, DM and HBP." (PMID 29234393, 2017). "Patient I:47 has a tumor which is MSI-H and present a loss of MLH1/PMS2 proteins, this patient has a VUS in MLH3, c.1870G > C, p.Glu624Gln." (PMID 27696107, 2017). "Because Mlh3;Pms2 deficiency also increased gastrointestinal tumor progression, we used array-CGH to identify a recurrent tumor amplicon." (PMID 18551179, 2008). "To understand the mechanistic contributions of MLH3 and PMS2 in gastrointestinal tumor suppression, we generated Mlh3−/−;Apc1638N and Mlh3−/−;Pms2−/−;Apc1638N (MPA) mice." (PMID 18551179, 2008). "In addition to major mismatch repair genes, MLH3, a newer member of the DNA mismatch repair family, also contributes to tumor development." (PMID 40356752, 2025). "In the observed tumor samples, the presence of MLH3 mutations did not correspond with microsatellite instability." (PMID 38201513, 2023). "Subsequently, tumors and matched non-tumor tissues were subjected to panel sequencing that revealed de novo somatic frameshift mutations in homopolymer regions of several genes including MSH3 and MLH3, confirming a defect in MMR in the tumor tissue." (PMID 31659152, 2019). "Investigating MMR gene mutations and methylation status in MSI tumor samples, we only observed few cases of MSH6 (MutSα), MSH3 (MutSβ), PMS2 (MutLα), PMS1 (MutLβ), and MLH3 (MutLγ) high-impact mutations often in combination with inactivation of other MMR genes." (PMID 29636374, 2018). "The MLH3 gene mRNA expression level was assayed in tumor tissues from 282 cases of CSCC." (PMID 24759751, 2014). "A candidate tumour suppressor gene, MLH3, has been identified on 14q24.3." (PMID 12107846, 2002). "With our sequencing approach we also detected a somatic MLH3 mutation in the MSI tumor, which, even though MLH3 mutations do not belong to the classical MMR mutations in CRC, might contribute to the microsatellite instability phenotype." (PMID 21203531, 2010). "We observed a significant association between OS and the expression of six genes (CCNH, MLH3, RAD51C, RPA3, SLK, and XPA) in primary tumor tissues." (PMID 37240218, 2023).
tumor (continued). "The methylation of the MLH3 promoter, the deletion of the NGR3 and NBN genes or chromothripsis on 13q observed in our study are potential phenomena that might influence tumor cell behavior and thus modulate the tumor’s responsiveness to treatment." (PMID 26865861, 2016). "The limited data indicates that MLH3-deficient tumours do not show MSI, and it is still unknown if they have a unique mutational signature as observed in neoplasms associated with other DNA repair defects." (PMID 40237887, 2025).
gastrointestinal tumors (4 papers, 2008 to 2021). "These are consistent with a role for Mlh3;Pms2 combined loss both to increase GI tumor initiation and accelerates progression." (PMID 18551179, 2008). "MLH3 deficiency causes MSI, impaired DNA damage response, increased gastrointestinal tumor susceptibility and significantly shorter lifespans compared to wild-type mice." (PMID 24759751, 2014). "To understand more precisely the mechanistic roles that Mlh3 and Pms2 play in GI tumor suppression, we generated Mlh3−/−;Apc1638N (MA) and Mlh3−/−;Pms2−/−;Apc1638N (MPA) mice." (PMID 18551179, 2008).
MLH3 also shares sentences with these, for which no sentence is quoted: colon cancer (2 papers); Hereditary nonpolyposis colorectal cancer (2); melanoma (2); metastatic disease (2); adenoma (1); anemia (1); colorectal (1); colorectal adenoma (1); diabetes (1); Familial adenomatous polyposis (1); Fanconi anemia (1); gastrointestinal carcinomas (1); hematological malignancies (1); hepatocellular carcinoma (1); hereditary cancer (1); hereditary cancer-predisposing syndrome (1); hereditary colorectal cancer (1); lung squamous cell carcinoma (1); Mendelian diseases (1); neurodegenerative disease (1); neurological disease (1); Obesity (1); prostate carcinoma (1); rectal tumors (1); renal cell carcinoma (1); skin cancer (1); Telangiectasia (1); thyroid cancer (1); triple-negative breast carcinoma (1).